BRCA1 (BRCA1 DNA repair associated)
Diseases named in the same sentence as BRCA1 in open-access papers (continued):
Sharing a sentence is not in itself a finding about the gene and the disease.
tumor (continued). "Notably, organoids derived from BRCA1-mutated tumours tended to exhibit a more limited growth, prompting early culture discontinuation – HGSC_1, HGSC_5 and HGSC_6." (PMID 40835947, 2025). "Interestingly, a recently published multi-centre real world study investigated the benefit of olaparib in 140 tumours based on BRCA1/2 mutation subtypes." (PMID 41228382, 2025). "In BRCA1/BRCA2-deficient tumor cells, the HR pathway is aberrant." (PMID 39885134, 2025). "Subsequently, in vivo studies on subcutaneous tumor xenografts in nude mice demonstrated that METTL1 knockdown could inhibit tumor growth, while overexpression of BRCA1 could reverse the inhibited tumor growth caused by METTL1 downregulation (all p < 0.0001)." (PMID 41430564, 2025). "Mechanistically, in BRCA1-deficient breast tumor cells, TAMs might adopt the pro-tumor polarization state, suppressing PARPi-induced DNA damage in tumor cells." (PMID 40075527, 2025). "The low prevalence of BRCA1/2 mutations within the HR+/HER2- subtype may suggest that other genetic or molecular mechanisms drive tumor development in this population." (PMID 40941615, 2025). "By synergistically integrating histopathological features from WSIs with clinical phenotypes from EHR through a unified latent representation space, MAIGGT achieves state‐of‐the‐art performance while providing novel biological insights into BRCA1/2‐associated tumor biology." (PMID 40439693, 2025). "Furthermore, the expression of molecules such as CD8, CD3, FOXP3, PD1, CTLA4, and GZMB is significantly increased in BRCA1 mutated tumor samples, signifying a robust T cell response in BRCA1 mutant TNBCs but a more prominent T cell exhaustion." (PMID 40830526, 2025). "Immune-mediated mechanisms of tumor development may be particularly relevant to BRCA1-driven neoplasms, as BRCA1 inactivation is associated with a deficiency in homologous DNA repair, chromosomal instability, and, consequently, increased tumor antigenicity." (PMID 41374957, 2025). "Breast cancer type 1 susceptibility protein (BRCA1) functions as a tumor suppressor essential for maintaining genomic integrity by coordinating several key cellular processes involved in genetic stability, such as DNA damage repair, cell cycle control, centrosome duplication, and apoptosis." (PMID 41208884, 2025). "Tumor‐specific factors, such as the immune microenvironment, immune evasion mechanisms, tumor aneuploidy, and the presence of specific mutations (e.g., BRCA1/2, PTEN, PBRM1, or JAK1), all contribute to ICI treatment outcomes, highlighting the necessity for a more comprehensive analysis of the TME." (PMID 40874420, 2025). "The literature indicates that olaparib can be cautiously preferred over capecitabine as adjuvant therapy in BRCA1/2 germline pathogenic variant TNBC cases as the PARPi directly targets the deoxyribonucleic acid (DNA) damage repair pathway implicated in this tumour subset." (PMID 40626017, 2025). "Notably, BRCA1 loss was significantly associated with aggressive disease features, including the diffuse histological subtype, high tumor grade, and advanced clinical stage." (PMID 40869030, 2025).
tumor (continued). "Due to the homologous recombination repair defect (HRD) caused by the mutation of the tumor BRCA1/2 gene, the DNA cannot be repaired by the base excision repair (BER) pathway and homologous recombination repair (HRR) pathway after the use of PARPi, which eventually leads to cell death." (PMID 41281744, 2025). "Reduced BRCA1 protein levels might result in insufficient or loss of BRCA1 function that contribute to BRCA1 deficiency and tumors with reduced protein levels of BRCA1 may share molecular features of BRCA1-mutant tumor and respond to PARPi therapy." (PMID 41359628, 2025). "BRCA1-mutated TNBC exhibits a unique tumor immune microenvironment characterized by higher mutational loads and extensive immune lymphocyte infiltration, suggesting that BRCA1 mutations could serve as potential biomarkers for ICI responses." (PMID 40904511, 2025). "Further in-vitro studies of ATM/BRCA1 double heterozygosity led to higher cell transformation rates, delayed recognition of DNA damage, aberrant DNA repair and increased genomic instability which promotes susceptibility to tumour initiation." (PMID 39843919, 2025). "However, we found that tumor mutation burden and predicted neoantigen counts were equivalent in BRCA1-deficient and BRCA2-deficient tumors between STS and LTS groups." (PMID 41255967, 2025). "RANK/RANKL inhibition is especially relevant for BRCA1 mutation carriers, while progesterone antagonists may assist in preventing tumor initiation in hormone-driven contexts." (PMID 40243654, 2025). "Targeting BRCA1-mutated breast cancer by restoring its function through homologous recombination repair (HDR) in combination with PARP inhibitors induced tumor cell apoptosis up to 70%, highlighting the therapeutic potential of precision editing for high-frequency driver mutations." (PMID 40697666, 2025). "As the patient had tested positive for the heterozygous pathogenic germline BRCA1 frameshift-variant NM_007294.4(BRCA1):c.843_846del (p.Ser282fs*15), resulting in a loss-of-function by nonsense-mediated decay, the case was also discussed in our molecular tumor board." (PMID 40519304, 2025). "In this exploratory analysis, we evaluated associations of tumor-infiltrating lymphocytes (TILs), T-cell‒inflamed gene expression profile (TcellinfGEP), BRCA1/BRCA2 mutation (BRCAm) status, homologous recombination deficiency (HRD) status, and tumor mutational burden (TMB) with clinical outcomes." (PMID 41038856, 2025). "Considering this evidence, our findings showing that DHA supplementation determines increased levels of RvD1 and RvD2 in specific subgroups—such as BRCA1/2-mutated patients—may reflect the activation of endogenous pro-resolving and anti-tumor pathways." (PMID 40427191, 2025). "However, tumour cells with BRCA1/2 mutations exhibit homologous recombination repair deficiency (HRD), relying instead on the error‐prone non‐homologous end joining (NHEJ) repair pathway." (PMID 40859871, 2025). "Research indicates that BRCA1/2 gene reverse mutations not only affect the DNA repair abilities of tumor cells but may also impact their sensitivity to other treatments." (PMID 40370464, 2025). "PARP inhibitors (PARPi) are effective in inhibiting tumor proliferation in BRCA1/2 mutated tumors." (PMID 41281744, 2025). "The BRCA1 gene encodes the BRCA1 protein, which functions as a tumor suppressor." (PMID 40283136, 2025). "Interestingly, both GATA3–METH and GATA–LOFDEL groups of tumours were significantly enriched in the gene signature of mutated BRCA1." (PMID 40585280, 2025). "Our data indicated that the expression of Smyd3 could be stimulated by ERα in synergy with the loss of Brca1 and enhance tumor outgrowth in nude mice with Brca1 mutant cells." (PMID 40157910, 2025). "Moreover, the representative confocal images of tumor tissues demonstrated that the loss of TOP1 induced an increase of γH2AX levels but a decrease of BRCA1 levels, consistent with the observation in CC cells." (PMID 39156107, 2024).
tumor (continued). "For instance, BRCA1 is tightly linked with many of the molecules involved in the epithelial–mesenchymal transition process, with this relationship being able to determine the appearance of aggressive tumor phenotypes like triple-negative variants." (PMID 39796670, 2024). "Indeed, in a CRISPR screen employing over 700 tumor cell lines including a subgroup with BRCA1/2 mutation and DNA repair defects, USP1 was found as a suitable target based on genetic dependency." (PMID 39430244, 2024). "Treatment based on molecular findings (PIK3CA mutation), genetic findings (BRCA1/2 germline mutation), or adapted to the change in the tumor phenotype in rebiopsy (anti-HER2 therapy in the transformation to HER-2-positive disease) was grouped into tailored treatment." (PMID 38912058, 2024). "Pathogenic variants (PVs) in BRCA1/2 genes can contribute to enhanced tumour angiogenesis." (PMID 39682099, 2024). "Further analysis of the Cancer Genome Atlas cohort identified four subtypes, with the C3 subtype having the highest immune signatures, an increased number of tumor-infiltrating immune cells, and a greater expression of immune checkpoints, particularly in patients with the BRCA1 mutation." (PMID 38543119, 2024). "This could be explained by the more favorable tumor characteristics in BRCA2 pathogenic variant carriers compared to BRCA1 and therefore the better prognosis in case of early detection." (PMID 38892081, 2024). "Recent investigations have revealed that approximately 25% of patients with mCRPC harbor tumor somatic or germline mutations in DNA damage repair (DDR) genes including breast cancer susceptibility genes BRCA1 and BRCA2, as well as other genes implicated in homologous recombination repair (HRR)." (PMID 37934252, 2024). "We now show that the same signatures may also be useful in identifying HR deficiency in GEA, a tumor type with far less frequent alterations in BRCA1/2." (PMID 38589664, 2024). "This is consistent with the presence of germline BRCA1 mutations in 2 of our patients, while the presence of signature 3 in the third patient's tumor could be due to epigenetic silencing of homologous recombination repair genes." (PMID 38315150, 2024). "Indeed, BRCA1/2-mutated tumors exhibit a higher mutational load, an increased amount of neoantigens, tumor-infiltrating lymphocytes, and PD-L1 expression." (PMID 38544832, 2024). "Overall, the tumor displayed a profile of unusual high genomic instability which suggests a possible origin from germline predisposing mutations in the DNA repair genes BRCA1 and RAD51." (PMID 38512353, 2024). "Knock-in mice bearing the Ile26Ala BRCA1 RING domain mutation (which compromises its E3 ligase activity but retains the ability to form heterodimer with BARD1) did not display any overt developmental defects or increased predisposition for developing tumours." (PMID 38985307, 2024). "Therefore, if a patient had a tumor BRCA1 mutation and the methylation status was missing, we assumed the BRCA1 promoter to be unmethylated, and vice versa." (PMID 38191387, 2024). "Therefore, they act as tumor suppressor genes, as mutations have been observed in tumor cells due to genomic instability, and approximately 80% of BRCA1 and 3–17% of BRCA2-related BC belong to the TNBC subtype." (PMID 38892472, 2024). "Furthermore, a high frequency of cells co-expressing basal and luminal specific markers (K8 + /K14 + cells) has been associated with malignancy in human Brca1-mutation carriers and in tumor mouse models." (PMID 38835038, 2024). "Tumor BRCA1 mutation (gBRCA1m or sBRCA1m) and tumor BRCA1-PM were mutually exclusive." (PMID 38191387, 2024). "Reconstitution of Gata3 enhances resistance of Brca1-deficient tumor cells to PARP inhibitor." (PMID 38627785, 2024). "In addition, the analysis of tumor DNA sometimes results in the finding of somatic mutatios, which occur in subjects with wild-type BRCA1/2 germ-line DNA." (PMID 38612902, 2024).
tumor (continued). "The tumor was reported to have a BRCA1 germline mutation and a MYC amplification." (PMID 38566237, 2024). "Thus, BRCA1-deficient tumor cells are hypersensitive to the combination of DNA-PK-i and PARP-i treatment." (PMID 38682589, 2024). "However, BRCA1/2 mutations are only present in 10.0–15.0% of OC, meaning that for most OC patients with BRCA1/2-proficient tumours, PARPi is less effective." (PMID 39768338, 2024). "Since PGF expression increases locally in the tumor milieu upon PARPi treatment, it is possible that a minor subpopulation of Brca1- and Bard1-deficient tumor cells that express the PGF receptor FLT1 prior to PARPi treatment becomes enriched in the PARPi-resistant tumors." (PMID 38956205, 2024). "Furthermore, case reports highlight the potential of combining PARP inhibition with immunotherapy in CCA with BRCA1/2 mutation and PD-1 overexpression, demonstrating promising anti-tumor efficacy." (PMID 38730642, 2024). "ML and DL models could be trained to predict the HRD status, as well as the presence of BRCA1/2 mutations, by providing an input dataset including tumor samples and the related genomic test results during the training process." (PMID 39220639, 2024). "CD8+ T cells have higher PD-1 expression in BRCA1/2 mutant tumours, which may enhance susceptibility to PD-1/PD-L1-targeted immune checkpoint therapy." (PMID 39530091, 2024). "Furthermore, if multiple copies of BRCA1 are present in a tumor, all copies must be methylated to develop a PARPi response, and the loss of only one methylated copy of BRCA1 is sufficient to restore HRR DNA repair and induce PARPi resistance." (PMID 37588193, 2024). "Moreover, there is an association of GMP with BRCA1 mutations and higher nuclear grade, both of which appear to increase tumor responsiveness to chemotherapy." (PMID 38818885, 2024). "Although we were readily able to establish RB1 knockout lines, all BRCA1 targeted clones were hemizygous for BRCA1 deletion and retained BRCA1 expression, suggesting that engineered homozygous loss of BRCA1 was cell lethal, even in a tumor type in which BRCA1 loss is frequently observed." (PMID 38837893, 2024). "Furthermore, it was observed that BRCA1 mutations appeared to be an unfavourable prognosticator only in tumours of intermediate stability." (PMID 39104056, 2024). "Furthermore, tumours showing homologous recombination deficiency, due to loss of BRCA1, BRCA2, PALB2 and CHEK2 function, have been shown to be especially sensitive to platinum-based chemotherapeutics and PARP inhibition." (PMID 36831687, 2023). "In OC, a few studies have linked certain bacterial species to tumor progression in BRCA1-mutated OC patients, although the specific mechanism remains unclear." (PMID 37121997, 2023). "It is suggested that the application of PARP inhibitors with PD-L1 inhibitors requires rigorous biomarker guidance, including BRCA1/2 mutations, PD-L1 expression levels in tumor tissues, tumor genomic microsatellite stability (MSS/MSI), and mutational load (TMB) assessment." (PMID 37864041, 2023). "Anti-angiogenic therapy could induce hypoxia in the tumor microenvironment, cause genetic instability and downregulation of BRCA1/2 and lead to HR deficiency, thereby potentiating response to PARP inhibitors." (PMID 37775744, 2023). "The last tumour (tumour 11) with a high HRDetect score contained both a somatic BRCA1 missense variant and a germline RAD51D variant of unknown significance." (PMID 37316882, 2023).
tumor (continued). "The limitation of relying upon upfront tumour BRCA1/2 testing to identify all possible pathogenic variants is that most local tumour NGS assays are not yet validated to detect whole gene/exon deletions or duplications, although Myriad’s myChoice® CDx does reliably detect these variants." (PMID 36765687, 2023). "To resolve this aspect of reciprocal pairs, we performed linked-read (LR) and standard WGS on 46 tumours and matched normal samples that were originally found by clinical panel sequencing to have inherited or somatic mutations in BRCA1 (27 cases) or BRCA2 (19 cases)." (PMID 37587346, 2023). "In addition, we report the prevalence of somatic BRCA1/2 pathogenic variants and tumours positive for HRD." (PMID 36765687, 2023). "In our study, three patients whose tumor had a BRCA1 mutation received PARPi therapy." (PMID 37173992, 2023). "Collectively, breast adipocytes may create a unique natural tumor niche for BC cells with germline mutations in BRCA1/2 genes." (PMID 36902416, 2023). "In GC, BRCA1 deficiency is significantly associated with patients with diffused Lauren type, higher tumor grades, and advanced clinical stage; these patients live significantly shorter than those with positive expression of BRCA1, indicating that loss of BRCA1 can serve as a prognostic marker." (PMID 37894343, 2023). "In fact, in preclinical models, mutations in Brca1 and Brca2 have been shown to influence response to immune checkpoint inhibitors (ICIs), with anti-PD-l blockade only improving survival of mice harbouring Brca1-null tumours." (PMID 38017453, 2023). "AZD5305 was most effective (tumor growth reduction, abdominal dissemination containment and survival gain) in OC-PDXs with underlying DNA repair deficits, such as deleterious mutations in BRCA1." (PMID 36994441, 2023). "Indeed, both preclinical and clinical studies have shown sensitivity to DSB inducing agents in BRCA1/2 mutated cells and tumours." (PMID 37029129, 2023). "Similarly, clear cell tumours provided somewhat greater evidence against BRCA1 variant pathogenicity before the age of 50 (LR: 0.16 (95% CI: 0.08–0.31), moderate evidence) versus over that age (LR: 0.37 (95% CI: 0.23–0.59), supporting evidence)." (PMID 37076566, 2023). "Patients with BRCA1/2 mutations may have distinct tumor characteristics and treatment responses, as they are more likely to develop TNBCs, which are typically more aggressive and may require tailored approaches." (PMID 38001690, 2023). "Thus, NORE1A forms a tumor suppressor complex with BRCA1, and NORE1A loss uncouples Her2+/BRCA1− cells from senescence induction." (PMID 37627161, 2023). "As for the loss of BRCA2, the model for loss of BRCA1 loss in ovary had sufficient predictive power (PR-AUC-E = 0.3) in the other data set, suggesting that the model works independently of the metastatic capacity of the tumour." (PMID 36883553, 2023). "The identification of three cases with germline BRCA1 mutations with somatic SHLD2 mutations in post-PARPi tumour samples suggests that through loss of the Shieldin complex, cells are diverted from NHEJ, restoring homologous recombination, leading to resistance." (PMID 38072854, 2023). "Tumor cells with BRCA1/2 mutations and HR deficiencies can be selectively targeted by PARPis." (PMID 37954854, 2023). "BRCA1/2 gene alterations are often genetically shared in familial context, but also food intake and hormonal assessment seem to influence the lifetime risk of developing this neoplasia." (PMID 37081976, 2023). "This should include analysing the mitotic phenotypes of BAP1-deficient cells in which BRCA1 expression is restored, as well as testing whether tumour cells undergoing mitotic progression are especially sensitive to loss of BAP1." (PMID 36550359, 2023). "Therefore, inactivation of the 53BP1-Shieldin pathway in BRCA1-deficient tumours confers PARPi resistance by restoring DNA end resection and homologous repair of DSBs." (PMID 37430137, 2023).